INSR (insulin receptor)
Diseases named in the same sentence as INSR in open-access papers (continued):
Sharing a sentence is not in itself a finding about the gene and the disease.
Insulin resistance (continued). "The fundamental molecular factor of insulin resistance may be impaired cell signal transduction mediated by the insulin receptor (IR)." (PMID 36589630, 2022). "InsR sensitizers can bind to the InsR to activate the insulin pathway independent of insulin; thus, InsR sensitizers have the potential to alleviate insulin resistance and minimize the risk of hypoglycemia." (PMID 35502441, 2022). "Downregulation of INSR expression can trigger insulin resistance." (PMID 35873798, 2022). "Insulin resistance is regulated by multiple factors under physiological conditions, including insulin, insulin receptor (InsR), insulin receptor substrate (IRS), glucose transporter 4 (GLUT4), as well as the Akt, mitogen activated protein kinase (MAPK), and AMPK pathways." (PMID 35330934, 2022). "Insulin sensitivity correlates with plasma insulin clearance, presumably because both insulin action in and insulin clearance by tissues require insulin binding to its receptors and insulin receptor expression is downregulated in people with insulin resistance." (PMID 35054781, 2022). "Furthermore, suppression of the insulin receptor signaling pathway by HFD-induced obesity or inflammation is a vital mechanism of insulin resistance." (PMID 36432581, 2022). "Furthermore, it can improve insulin resistance and oxidative stress by affecting insulin receptor signaling pathways and adjusting the structure of the intestinal microbiome." (PMID 35833030, 2022). "Down-regulation of insulin receptor is a well-established contributor to insulin resistance." (PMID 34996843, 2022). "However, long-term persistence of high levels of FFA is most likely to promote insulin resistance by inhibiting tyrosine phosphorylation of insulin receptor and IRS-1." (PMID 33841146, 2021). "It is noteworthy that low intracellular Mg2+ impairs cell responsiveness to insulin, because low intracellular Mg2+ alters the tyrosine-kinase activity of the insulin receptor (INSR), leading to the development of post-receptor insulin resistance and decreased cellular glucose utilization." (PMID 33499378, 2021). "Insulin resistance, regarded as another representative pathological feature of metabolic disorders, aggravating on account of the inhibition of the insulin receptor substrates (Irs) pathway, could also be regulated by AMPK signaling pathway." (PMID 33936248, 2021). "It has been suggested that abnormal EV from different cells could induce insulin resistance through activating inflammation, affecting the insulin receptor and down-regulating glucose transporter type 4 (GLUT-4)." (PMID 33477341, 2021). "Meanwhile, inflammatory response is also an important mechanism causing insulin resistance, which may be related to inflammatory factors acting on INSR to change the phosphorylation site and process, and eventually lead to insulin resistance." (PMID 34516329, 2021). "It has been defined that brain insulin resistance occurs primarily with early hyperactivation of insulin signaling, including mTOR hyperactivity, which causes negative feedback on the insulin receptor, IRS1 and mTOR itself." (PMID 34065168, 2021). "Any impairment of the relationship between INS and INSR will lead to insulin resistance." (PMID 33549051, 2021). "With this background, in this paper, we analyzed whether the severe hepatic insulin resistance of inducible liver-specific insulin receptor knockout (iLIRKO) mice expands to the cardiovascular system, inducing insulin resistance in aorta artery and heart." (PMID 34440804, 2021). "Hence, TNF-α is well known to be an important mediator of insulin resistance in adipose tissue through insulin-receptor signaling in rodents and humans." (PMID 33954196, 2021). "TXNIP is a mediator of insulin resistance in liver, skeletal muscle and adipose tissue, and impaired pancreatic beta-cell insulin secretion and TNFα decreases insulin receptor signaling in adipose tissue and skeletal muscle, particularly prior to development of T2DM." (PMID 34371884, 2021).
Insulin resistance (continued). "Furthermore, TNF-α inhibits AMP-activated protein kinase (AMPK) signaling in muscle and insulin receptor autophosphorylation in fat tissue and the liver, which promotes insulin resistance." (PMID 33807573, 2021). "These events disrupt insulin receptor signaling cascades and promote insulin resistance." (PMID 34863096, 2021). "The proinflammatory cytokines may induce insulin resistance through unrestrained production of insulin receptor substrate." (PMID 34344352, 2021). "The decrease in insulin receptor may induce insulin resistance and reduction of capillaries in aged ECs." (PMID 35004685, 2021). "Second, obesity is linked to insulin resistance, and the most crucial factor in modifying insulin sensitivity is the release of non-esterified fatty acids which diminish insulin receptor signaling." (PMID 33986312, 2021). "TNFα also contributes to insulin resistance by inhibiting insulin receptor signaling." (PMID 33924165, 2021). "Moreover, O-ADSC treatment also tended to attenuate insulin resistance which coincided with the restoration of INSR expression in the muscle." (PMID 33957965, 2021). "In particular, tumor necrosis factor alpha plays a major role in hepatic insulin resistance, and it inactivates the insulin receptor substrate by serine phosphorylation through activation of a serine/threonine kinase, thus blocking the insulin receptor signaling cascade." (PMID 34463983, 2021). "VD3 was shown to enhance insulin synthesis and release, increase insulin receptor expression and inhibit the production of proinflammatory cytokines that might counteract the development of insulin resistance." (PMID 33095902, 2021). "Periodontitis‐related systemic inflammation may contribute to insulin resistance through elevated blood levels of adipocytokines, such as tumor necrosis factor alpha, IL‐6, and leptin, which inhibit the insulin receptor and its downstream signaling." (PMID 34463983, 2021). "The regulation of insulin receptor ubiquitination is one of the mechanisms of insulin resistance." (PMID 34603025, 2021). "The insulin resistance observed in DUSP3-KO mice suggests that this phosphatase could play a role in insulin receptor (IR) signaling." (PMID 33712680, 2021). "This notion is supported by the characterization of type B insulin resistance, where a high aAb load to the insulin receptor may constitute a life-threatening condition." (PMID 33946552, 2021). "With the increased understanding of the insulin receptor signaling pathways came the realization in the early 2000s that phosphorylation of specific insulin receptor substrates and cross-talk with other signaling pathways can contribute to insulin resistance." (PMID 34717951, 2021). "A second mechanism could be via impaired signalling pathways from the insulin receptor which may link insulin resistance in DCM with impaired cardiomyocyte function." (PMID 34113491, 2021). "Further studies are required to investigate whether ALM extract or its pure compounds protect against the development of insulin resistance by increasing IGF1R activity or whether it exerts direct inhibitory effect on INSR is involved." (PMID 34483915, 2021). "Antagonizing both miR-1983 and miR-7 in specific neuronal subtypes may have therapeutic potential as preventing the downregulation of the InsR is one potential way to combat hypothalamic insulin resistance." (PMID 34831343, 2021). "YLNKYLGDV could potentially be processed from transmembrane glycoprotein ectonucleotide pyrophosphatase phosphodiesterase 1 (ENPP1) protein, a key player involved in inhibiting insulin receptor signaling and the development of insulin resistance." (PMID 32425926, 2020). "In addition, high concentrations of FK-506 can inhibit the binding of insulin receptor, exacerbating insulin resistance." (PMID 32352504, 2020).
Insulin resistance (continued). "The low and high dose of acacetin observably reduced the level of (Ser612) p-IRS-1 (P < 0.01), indicating that the improvement of insulin resistance in SHR(F) rats by acacetin may be related to the inhibition of insulin receptor phosphorylation at Ser612." (PMID 32892299, 2020). "T2DM is characterized by insulin resistance which may be due to insulin receptor and/or postreceptor defects." (PMID 32655759, 2020). "Insulin receptor autoantibodies have three mechanisms that lead to insulin resistance." (PMID 32813762, 2020). "We used a combination of analytical techniques (immunoprecipitation, cross-linking, and fluorescence recovery after photobleaching (FRAP)) in living cells, to demonstrate that the increased GM3 level in the state of insulin resistance dissociated InsR from caveolin-1." (PMID 32731387, 2020). "This study aimed to investigate the effects and mechanisms of magnesium supplementation on insulin receptor activity in elderly type 2 diabetes using a rat model and to provide experimental evidence for insulin resistance improvement by magnesium supplementation." (PMID 32952944, 2020). "Moreover, under insulin resistance conditions, DCDC2 displayed increased association with the INSR, and the disruption of microtubules led to complete loss of this interaction." (PMID 33458251, 2020). "Atypical splicing of the insulin receptor (IR) may take part in the formation of insulin resistance." (PMID 33255644, 2020). "Complement C3 and other adipokines may promote insulin resistance (IR) by increasing phosphorylation and proteosomal degradation of insulin receptor substrates or by disturbing insulin receptor-substrate interaction." (PMID 33221761, 2020). "The increased mortality in patients with T2DM might be explained by the effect of insulin resistance or hyperinsulinemia, since breast cancer cells might have a selective growth advantage because of insulin receptor overexpression." (PMID 33198768, 2020). "Together, these results suggest that miR-378b controls insulin sensitivity by targeting the insulin receptor (IR) as well as p110α and possibly play an inhibitory role in the development of insulin resistance, thereby providing insights into the development of novel diagnostic and treatment methods." (PMID 32508647, 2020). "Hyperglycemia can lead to insulin resistance through post-insulin receptor defects." (PMID 32266256, 2020). "Another is a more indirect scenario by way of TNF-α via stimulating SOCS3 and in turn SOCS3 through affecting the insulin receptor substrate complex leading to the inhibition of the insulin/insulin receptor-mediated pathway, finally resulting in increased adipocyte insulin resistance." (PMID 31940889, 2020). "Mutations of INSR should be kept in mind in patients with severe insulin resistance but without metabolic dyslipidemia, low SHBG level and hepatosteatosis." (PMID 32018348, 2020). "Insulin resistance is partly mediated by reducing levels of insulin receptor expression." (PMID 32047529, 2020). "Insulin resistance could lead to apoptosis by disruption of a secondary pathway; insulin receptor phosphorylation which disrupts long term potentiation, thus increasing inflammation and generating oxidative stress." (PMID 33096995, 2020). "Mutations on the insulin receptor have been identified in several conditions such as leprechaunism, Rabson-Mendenhall syndrome, or the type-A syndrome of insulin resistance, but have not been observed in patients with typical DM type 2." (PMID 30717446, 2019). "Although the pathological mechanism is presently unclear, the insulin resistance has been attributed to changes in insulin signalling that occur downstream from the insulin receptor in the insulin receptor substrate (IRS), phosphatidylinositol-3-kinase (PI3K) and protein kinase B (AKT) pathway." (PMID 31195596, 2019). "Caveolin-3 knockout mice showed global insulin resistance accompanied by attenuated INSR functions." (PMID 31658625, 2019).
Insulin resistance (continued). "Emerging evidences suggest that disruption of INSR can directly result in insulin resistance." (PMID 31658625, 2019). "Such alterations may exaggerate insulin response in the short term due to INSR retention on the plasma membrane, but may lead to a long-term decrease in INSR membrane expression due to reduced INSR recruitment and development of insulin resistance." (PMID 31658625, 2019). "Impaired INSR endocytosis due to increased viscosity and disrupted lipid orientation of the plasma membrane exerts a direct effect on decreased insulin action and development of insulin resistance." (PMID 31658625, 2019). "Collectively, these findings might suggest a potential role of PLCXD3 in the development of insulin resistance by diminishing the expression of INSR and GLUT2, thus resulting in β-cell dysfunction." (PMID 31781030, 2019). "Alternative translation initiation of caveolin-2, a building block of caveolae, may promote the dephosphorylation of INSR by PTP1B and cause insulin resistance." (PMID 31658625, 2019). "Impairment in serine/threonine phosphorylation of insulin receptor substrate proteins leads to insulin resistance, which could have pathophysiological implications in CP." (PMID 31035542, 2019). "Moreover, DAG PKC activation contributes to lipid-induced hepatic insulin resistance through phosphorylation and the consequent inhibition of the insulin receptor." (PMID 31788032, 2019). "Accumulating evidence suggests that alterations in INSR trafficking may lead to severe insulin resistance." (PMID 31658625, 2019). "Decrease of INSR will eventually lead to cell dysfunction and insulin resistance." (PMID 31658625, 2019). "Accumulation of the intracellular lipid species diacylglycerol and ceramide are thought to contribute to hepatic insulin resistance by activating PKCε and protein phosphatase 2a (PP2a), respectively, resulting in inhibition of the insulin receptor signaling cascade." (PMID 31724300, 2019). "As shown in both in vivo and in vitro studies, disruption of INSR endocytosis may contribute to insulin resistance." (PMID 31658625, 2019). "Recent findings have revealed that different distributions of INSR and an altered INSR-A:INSR-B ratio may contribute to metabolic abnormalities during the onset of insulin resistance and the progression to type 2 diabetes." (PMID 30754657, 2019). "Risk alleles like FTO, ADIPOQ, INSR, IRS1, IRS2, PPARG, CAPN10 may leave individuals more vulnerable to insulin resistance and/or adiposity (which can result in peripheral insulin resistance), leading to high circulating insulin." (PMID 31367382, 2019). "Recent studies have confirmed that short-term exposure to high glucose significantly decreased the binding affinity of insulin to caveolin-1 and INSR in mature adipocytes, which might contribute to the development of insulin resistance in early T2DM." (PMID 31658625, 2019). "In literature, the studies aimed to define DM insulin resistance driving mechanisms provided evidences that in addition to aberrant splicing of INSR gene, defects in post-receptor insulin signalling might contribute to this feature of the disease." (PMID 30901379, 2019). "Functionally significant variation in genes encoding the canonical signaling components (e.g., insulin receptors, insulin receptor substrates, Akt) have been identified in severe inherited insulin resistance, and, although extremely rare, they have been quite informative." (PMID 30357355, 2019). "Failure on effective insulin clearance dramatically increases insulin action in the short term, whereas in the long term it leads to decreased amounts of INSR on the plasma membrane and contributes to the progression of insulin resistance and further into T2DM." (PMID 31658625, 2019). "However, there is very little understanding of how altered INSR activities undermine complex signaling pathways to the development of insulin resistance and T2DM." (PMID 31658625, 2019).
Insulin resistance (continued). "Thus, impaired insulin receptor signaling contributes to the development of hippocampal insulin resistance (IR)." (PMID 31291963, 2019). "By studying the endocytosis of INSR, potential therapeutic targets may be identified to overcome insulin resistance." (PMID 31658625, 2019). "Indeed, the gut microbiota can produce short-chain fatty acids (SCFAs) as metabolites from the host diet that bind to specific GPCRs and confer insulin resistance through biased activation of insulin receptor (IR) signaling." (PMID 30884834, 2019). "Thus even though fetuin-A does not bind to the same site as insulin on the extracellular portion of InsR, it attenuates insulin signaling, thereby contributing to insulin resistance." (PMID 30060600, 2018). "If insulin resistance or disturbance of InsR occurs, GSIS-related signalling pathways may be affected and β-cell dysfunction may occur, including disturbances in insulin synthesis and secretion." (PMID 29587416, 2018). "ROS play a crucial role in the progression of inflammatory disorders and its increased production may contribute to alterations of insulin/insulin receptor substrate signaling pathways leading to insulin resistance and inflammatory settings." (PMID 30024959, 2018). "Systemic insulin resistance induced in mice as a result of HFD reduces insulin receptor genes, insulin sensitive glucose transporter proteins, and activation of downstream effectors of insulin signaling pathways, such as phosphatidylinositol-3-kinase (PI3K) and Akt, in the hippocampus." (PMID 30619085, 2018). "By preventing insulin receptor dimerization, lipid raft alterations are suggested to play a role in development of insulin resistance, and DM may arise as a consequence of an unbalanced membrane sphingolipid composition." (PMID 29922223, 2018). "Another contributing factor to insulin resistance may be production of TNFα during infection, since this cytokine inhibits insulin receptor signaling." (PMID 30161232, 2018). "However, liver-specific insulin receptor knockout (LIRKO) mice exhibit severe insulin resistance and dramatic glucose intolerance." (PMID 30692925, 2018). "Chronic HS feeding also produces insulin resistance in adult flies, and flies with a compromised gut barrier exhibit impaired insulin signaling, with a reduced degree of Akt phosphorylation, despite increased insulin receptor expression." (PMID 30504122, 2018). "This target was identified as a potential target of 17 metabolites of sibirioside A and angoroside C. Defects in INSR cause insulin resistance, leprechaunism, noninsulin-dependent diabetes mellitus, and familial hyperinsulinemic hypoglycemia." (PMID 30347747, 2018). "Longitudinal studies suggest a steep relationship between residual INSR function and clinical outcome: loss of 50% INSR function, as in the parents of infants with Donohue syndrome, does not produce insulin resistance in lean people." (PMID 29700562, 2018). "These cytokines may promote insulin resistance by increasing the phosphorylation and proteosomal degradation of insulin receptor substrates or by affecting the insulin receptor-substrate interaction." (PMID 30454064, 2018). "Several studies suggested that lipids could induce insulin resistance in liver and skeletal muscle by interfering with downstream signal transduction of the insulin receptor." (PMID 29046729, 2017). "Induction of insulin resistance in experimentally aged rats was evidenced by increased blood glycated hemoglobin, brain contents of insulin and receptors for advanced glycated end-products, as well as decreased brain insulin receptor level." (PMID 28832656, 2017). "Furthermore, M1 macrophages secrete pro-inflammatory cytokines including TNFα, IL-1β, and IL-6, some of which can directly alter insulin receptor signaling in adipocytes, leading to insulin resistance." (PMID 29163218, 2017).